BIN1 (bridging integrator 1)
Diseases named in the same sentence as BIN1 in open-access papers (continued):
Sharing a sentence is not in itself a finding about the gene and the disease.
multiple sclerosis (3 papers, 2016 to 2025). A progressive autoimmune disorder affecting the central nervous system resulting in demyelination. "The results from three BIN1 antibodies reveal the high degree of similarity between BIN1 labeling intensity and the extent of myelin loss in multiple sclerosis lesions." (PMID 27488240, 2016). "Also, the loss of BIN1 parallels myelin loss in multiple sclerosis brain lesions neurodegeneration, and DDX5 is involved in MBP regulation." (PMID 40943121, 2025). "Finally, we show that the loss of BIN1 immunoreactivity closely parallels myelin loss within brain lesions of individuals with multiple sclerosis in a pilot study." (PMID 27488240, 2016). "Finally, we document that the loss of BIN1 significantly correlates with the extent of demyelination in multiple sclerosis lesions." (PMID 27488240, 2016). "The upregulation of BIN1 during in vitro oligodendrocyte maturation and the period of myelination in vivo, and the loss of BIN1 within brain lesions of patients with multiple sclerosis are all consistent and point to a potential role for BIN1 in mature oligodendrocytes in the brain." (PMID 27488240, 2016). "We also analyzed the similarities in Luxol fast blue and BIN1 staining intensities in active multiple sclerosis plaques with demyelination and activated macrophages, and in shadow plaques where the axons maintain uniformly thin myelin sheaths." (PMID 27488240, 2016). "The diminution of BIN1 within chronic lesions and its reemergence during remyelination within the multiple sclerosis lesions are consistent with BIN1 expression in myelinating oligodendrocytes." (PMID 27488240, 2016). "In a pilot study, we performed BIN1 labeling of autopsy brain samples from a set of confirmed cases of multiple sclerosis and compared the results to the staining of Luxol fast blue, a commonly used myelin stain." (PMID 27488240, 2016). "In agreement, our analysis of brain tissue from patients with multiple sclerosis shows a close correlation between BIN1 levels and the intensity of myelin labeling across the different types of lesions." (PMID 27488240, 2016). "The association of reduced BIN1 expression with demyelination processes is characteristic of CSVD due to ischemia/hypoxia in the area of stenosed small vessels and vasogenic edema due to the BBB damage, as has been established in multiple sclerosis." (PMID 39125683, 2024).
Myotonia (3 papers, 2014 to 2025). An involuntary and painless delay in the relaxation of skeletal muscle following contraction or electrical stimulation. "Particularly, missplicing of muscle chloride channel (CLCN1), insulin receptor (INSR), bridging integrator 1 (BIN1) and calcium channel voltage-dependent L type alpha 1S subunit (CACNA1S) results in myotonia, insulin resistance and muscle weakness, respectively, constituting key hallmarks of DM." (PMID 25183524, 2014). "Whereas some parameters like myotonia and Atp2a1 exon 22 inclusion displayed a sort of all-or-nothing effect, others exhibited a more graded correlation with transgene expression, such as miR-218 relative expression and Bin1 exon 11 inclusion." (PMID 40016516, 2025).
non-small cell lung carcinoma (3 papers, 2019 to 2025). A group of at least three distinct histological types of lung cancer, including non-small cell squamous cell carcinoma, adenocarcinoma, and large cell carcinoma. "Wang and colleagues also found a role for BIN1 in inhibiting tumor immune escape in non-small cell lung cancer (NSCLC)." (PMID 33801599, 2021). "The expression of CDK5 and BIN1 in non-small cell lung cancer (NSCLC) cell lines were measured." (PMID 31496920, 2019).
Obesity (3 papers, 2021 to 2025). Accumulation of substantial excess body fat. "The expression of various genes was also causally associated with the risk of AD, confirming ACE and BIN1 as risk genes for AD, while a genetically predicted anti-obesity drug target gene CNR1 was a protective factor against AD risk." (PMID 40082927, 2025). "An even more pronounced reduction was observed for Eif5, whereas expression of Tcf25 and Bin1 were not altered by diet-induced obesity." (PMID 33257475, 2021).
Ventricular arrhythmia (3 papers, 2020 to 2025). "The loss of the BIN1 scaffold in BIN1 knockout mice was manifested by prolongation of the action potential and increased probability of ventricular arrhythmia." (PMID 40352140, 2025). "Another circulating marker is bridging integrator 1 (BIN1) which was associated with ventricular arrhythmias in AC patients with HF but lacked specificity." (PMID 32899376, 2020). "Thus, the BIN1 defect does not have a dose-dependent effect in skeletal muscle, unlike in the heart in which it causes T-tubule defects and an increasing susceptibility to ventricular arrhythmias." (PMID 32994313, 2020).
virus infection (3 papers, 2016 to 2024). "For example, BIN1 binds to SARS-CoV-2 to block viral infection, whereas CD33 increases SARS-CoV-2 susceptibility and infection severity because of its immunosuppressive effect." (PMID 37962454, 2024). "On the other hand, the Cterminus contains Src-homology 3 (SH3) binding motifs for the localization of cellular amphiphysins Amph1 and BIN1/Amph2 following virus infection which promote Alphavirus genome replication." (PMID 27812412, 2016). "The cardiac conduction related proteins BIN1 and TPM1 are downregulated in the cardiomyocytes of COVID-19 hearts compared with the control samples, suggesting the virus infection could cause a serious impact on the systolic and diastolic functions of heart." (PMID 38087340, 2023). "For example, upregulated levels of APP, BIN1, and INPP5D are connected with increases AD risks but play inhibitory roles in some viral infections." (PMID 37962454, 2024).
breast tumors (2 papers, 2007 to 2020). "BIN1 expression losses were detected in MCF7 and T47D cells and were characteristic of primary breast tumors (10/13; 77%), while loss of heterozygosity was a rare event in tissue samples (2/22 informative cases; 9%) and was ruled out for MCF7." (PMID 17477881, 2007). "On the other hand, the splicing factor SRSF1 has been observed to be upregulated in breast tumors acting as an oncogene by producing impaired splicing isoforms of the pro-apoptotic genes BCL2 Like 11 (BIM) and the Bridging integrator 1 (BIN1) which are involved in the tumoral phenotype." (PMID 32635183, 2020).
COVID-19 (2 papers, 2022 to 2023). A disease caused by infection with severe acute respiratory syndrome coronavirus 2. "Among them, an overlap has been found between genetic risk factors for AD and severe COVID-19, such as single-nucleotide polymorphisms (SNPs) in oligoadenylate synthetase 1 (OAS1) and bridging integrator 1 (BIN1) genes." (PMID 35055344, 2022).
dilated cardiomyopathy (2 papers, 2021 to 2022). Cardiomyopathy which is characterized by dilation and contractile dysfunction of the left and right ventricles. "Our results show that decreased PC1 expression in cardiomyocytes induces dilated cardiomyopathy associated with diminished BIN1 expression and T-tubule remodeling." (PMID 36614108, 2022). "Cardiac conditional BIN1-deleted adult mice show loss of T-tubule microfolds, increases in T-tubule luminal diameter, impaired cardiac excitation–contraction coupling and cardiac contractility, reduced Cav1.2 protein levels, and over time develop dilated cardiomyopathy." (PMID 36614108, 2022). "Since BIN1 organizes the T-tubule membrane calcium handling microdomains required for normal muscle contraction and T-tubule remodeling occurs early in the development of HF of varying etiology, including dilated cardiomyopathy, BIN1 gene therapy could rescue cardiac function in failing hearts." (PMID 36614108, 2022).
dyslipidemia (2 papers, 2022 to 2025). "Additionally, there was a significant risk of dyslipidemia for APOE ε4 carriers (OR = 1.804; p = 0.036), whereas BIN1 rs744373 risk-allele carriers were at a significantly lower risk of having dyslipidemia (OR = 0.558; p = 0.006)." (PMID 39081475, 2022).
gastric cancer (2 papers, 2012). A primary or metastatic malignant neoplasm involving the stomach. "The authors also identify the molecular substrate called bridging integrator 1 (BIN1) to act as a potent predictor of cisplatin sensitivity in gastric cancer treatment." (PMID 22928098, 2012).
hepatocellular carcinoma (2 papers, 2024). A malignant tumor that arises from hepatocytes. "Similarly, the DHX9-NONO-SFPQ complex regulates the oncogenic splicing switch of BIN1 in hepatocellular carcinoma." (PMID 39048555, 2024). "In hepatocellular carcinoma, NONO is implicated in the production of a long isoform of bridging integrator 1 (BIN1) through exon 12a inclusion, contributing to enhanced malignancy." (PMID 38303029, 2024).
hippocampal atrophy (2 papers, 2021 to 2025). "For example, a BIN1 gene mutation can cause changes in internal olfactory structures and lead to hippocampal atrophy." (PMID 34733192, 2021).
lung adenocarcinoma (2 papers, 2015 to 2025). A carcinoma that arises from the lung and is characterized by the presence of malignant glandular epithelial cells. "Additionally, further analysis of the CPTAC database revealed significantly reduced BIN1 expression levels in both lung adenocarcinoma (LUAD) and lung squamous cell carcinoma (LUSC)." (PMID 40346580, 2025).
psychosis (2 papers, 2024 to 2026). "BIN1 and EPHA1 have been linked to psychosis, whereas NME8 has been inversely associated with apathy." (PMID 38473892, 2024). "Associations with APOE and MS4A for affective dysregulation, ZCWPW1, EPHA1, and BIN1 for psychosis-related symptoms, and NME8 for apathy highlight the possibility that MBI domains represent clinically observable phenotypes of underlying genetic susceptibilities." (PMID 41591092, 2026). "Therefore, it can be speculated that BIN1 may mediate the link between tau neuropathology and psychosis in AD, although further evidence is needed especially for the presymptomatic stages." (PMID 38473892, 2024). "The Apolipoprotein E (APOE) genotype and the MS4A locus have been associated with affective dysregulation, ZCWPW1 with social inappropriateness and psychosis, BIN1 and EPHA1 with psychosis, and NME8 with apathy." (PMID 38473892, 2024).
skeletal myopathies (2 papers, 2017 to 2021). "For example, skeletal BIN1 isoforms (BIN1+11+17 or BIN1+11) contain a phosphoinositide-binding domain encoded by exon 11, which is responsible for organizing skeletal t-tubule membrane and is mutated or mis-spliced in patients with skeletal myopathy." (PMID 28806752, 2017).
Atrophy (1 paper, 2025). Any weakening or degeneration, especially through lack of use. "This study presents novel findings indicating an association between the BIN1 rs10200967 genotype and lHATA atrophy, with the rs10200967 CC genotype showing a higher volume of lHATA in individuals with MCI." (PMID 40012995, 2025).
autoimmune disease (1 paper, 2018). A disorder resulting from loss of function or tissue destruction of an organ or multiple organs, arising from humoral or cellular immune responses of the individual to their own tissue constituents. "MLH3 and BIN1 gene have shown to be associated with Lupus, another severe autoimmune disease." (PMID 30666269, 2018).
Brain atrophy (1 paper, 2019). Partial or complete wasting (loss) of brain tissue that was once present. "Another possibility suggested by the genetic relationship between BIN1 AD-associated SNPs and brain atrophy is that the loss of neuronal Bin1 was causally linked to neuronal loss." (PMID 31408457, 2019). "BIN1 AD-associated SNPs correlate with Tau deposition as well as with brain atrophy." (PMID 31408457, 2019).
central neurocytoma (1 paper, 2022). A benign brain tumor composed of neural elements which most often arise from the SEPTUM PELLUCIDUM and the walls of the lateral ventricles. "A microarray-based comparative genomic hybridization investigation revealed distinct profiles, with loss and gain of multiple chromosomal loci, which concluded that MYCN gene amplification, together with loss of BIN1 expression, were typical of central neurocytoma." (PMID 35663322, 2022).
cholangiocarcinoma (1 paper, 2025). A carcinoma that arises from the intrahepatic biliary tree (intrahepatic cholangiocarcinoma) or from the junction, or adjacent to the junction, of the right and left hepatic ducts (hilar cholangiocarcinoma). "Beyond VEGF, SRPK1 inhibition alters the splicing of MCL1/BIN1/BCL2 to produce pro-apoptotic isoforms in cholangiocarcinoma and causes stress-associated cell death in lymphoma." (PMID 41551143, 2025).
cutaneous T-cell lymphoma (1 paper, 2025). "In cutaneous T-cell lymphoma, researchers have observed decreased BIN1 expression alongside increased c-FLIP expression." (PMID 40016843, 2025).
familial cardiomyopathy (1 paper, 2010). An instance of cardiomyopathy that is caused by an inherited modification of the individual's genome. "In mice, BIN1 knockout causes perinatal lethal cardiomyopathy, and a mutation in the same 2q14-22 locus of BIN1 is associated with familial cardiomyopathy in humans." (PMID 20169111, 2010).
frontotemporal dementia (1 paper, 2024). Frontotemporal dementia (FTD) comprises a group of neurodegenerative disorders, characterized by progressive changes in behavior, executive dysfunction and language impairment, as a result of degeneration of the medial prefrontal and frontoinsular cortices. "Additionally, hypomethylation of the BIN1 gene at specific CpGs (26, 44, and 87) in the blood has been associated with an increased risk of LOAD, while hypermethylation of the PIN1 gene promoter distinguished frontotemporal dementia (FTD) from the hypomethylation observed in AD." (PMID 39678047, 2024).
Gaucher disease (1 paper, 2022). Gaucher disease (GD) is a lysosomal storage disorder encompassing three main forms (types 1, 2 and 3), a fetal form and a variant with cardiac involvement (Gaucher disease - ophthalmoplegia - cardiovascular calcification or Gaucher-like disease). "Still, a number of risk factors for LBD are linked to other neurodegenerative diseases: BIN1 (also AD), TMEM175 (Transmembrane protein 175; also PD), SNCA (also PD), APOE (also AD), and GBA (glucocerebrosidase; also PD, Gaucher’s disease)." (PMID 36421678, 2022).
HIV-1 infection (1 paper, 2020). The type species of lentivirus and the etiologic agent of acquired immunodeficiency syndrome (AIDS). "A role for BIN-1 in HIV-1 infection is supported further by a study that identifies the upregulation of BIN-1 in CD4+ and CD8+ T cells from ex vivo patients." (PMID 32075937, 2020).
hypertrophic cardiomyopathy (1 paper, 2015). A condition in which the myocardium is hypertrophied without an obvious cause. "Conversely, mouse C2C12 skeletal myoblasts fail to differentiate following downregulation of Bin1, and Bin1 homozygous knock-out mice develop hypertrophic cardiomyopathy leading to perinatal lethality, although skeletal muscles do not exhibit any apparent abnormalities at this stage." (PMID 25961035, 2015).
inflammatory bowel disease (1 paper, 2023). A spectrum of small and large bowel inflammatory diseases of unknown etiology. "Interestingly, before AD emerges in the brain, tau levels rise in the colon, where Bin1—a modifier of tissue barrier function and inflammation—acts to promote inflammatory bowel disease (IBD)." (PMID 37521457, 2023).
learning disabilities (1 paper, 2022). "BIN1 is known to contribute to the select impairment of spatial learning and memory, possibly contributing to learning disabilities observed in ASD." (PMID 36817099, 2022).
leprosy (1 paper, 2013). Leprosy is a chronic infectious disease affecting primarily the skin and peripheral nervous system. "Thus BIN-1 remained most strongly associated with susceptibility to leprosy." (PMID 23861666, 2013).
metastatic tumors (1 paper, 2007). "RNA and immunohistochemical analyses indicate that BIN1 is expressed in most primary prostate tumors, even at slightly elevated levels relative to benign tissues, but that it is frequently missing or inactivated by aberrant splicing in metastatic tumors and androgen-independent tumor cell lines." (PMID 17477881, 2007).
multiminicore disease (1 paper, 2022). "For example, CNM has been associated with at least seven genes, including MTM1, DNM2, RYR1, TTN, BIN1, CCDC78 and SPEG, whereas RYR1 variations can cause central core disease (CCD), multiminicore disease (MmD), core-rod myopathy, CNM and CFTD." (PMID 35081925, 2022).
Myalgia (1 paper, 2021). "All CNM patients had at least one motor symptom (signs of delayed gross motor development, muscle weakness, muscle atrophy, and hypotonia), except for two BIN1 patients whose main clinical features were myalgia and muscle cramps." (PMID 34463354, 2021). "Myalgia and cramps were reported by many BIN1 patients and female MTM1 carriers, while fatigue and exercise intolerance were common in all groups of CNM." (PMID 34463354, 2021).
myocarditis (1 paper, 2010). Myocarditis is a condition that is characterized by inflammation of the heart muscle (myocardium). "As cardiac abnormalities have been reported for another ARCNM patient who died from myocarditis shortly after birth, we suggest careful cardiac function examinations and long term follow-up of patients with BIN1 mutations." (PMID 21129173, 2010).
neuropathic pain (1 paper, 2025). Chronic pain caused by damage to nerve fibers. "BIN1, a membrane-sculpting protein implicated in neurodegenerative disorders, has been shown to regulate microglial priming and synaptic integrity, suggesting that it may serve as a mechanistic link between glial activation and synaptic remodeling in neuropathic pain." (PMID 40650236, 2025).
ophthalmoplegia (1 paper, 2020). Weakness or paralysis of at least one of the muscles controlling the movement of the eye. "The autosomal recessive form of CNM with the onset of weakness in infancy or early childhood with or without ophthalmoplegia (OMIM 255200) was termed CNM2 and is due to mutations in the BIN1 gene." (PMID 32164332, 2020).
oral cancer (1 paper, 2020). "Overexpression of BIN1 protein in OSCC cell lines is associated with decreased proliferation and migration, suggesting that miR-211 may be a new target in treatment of oral cancer." (PMID 31712935, 2020).
pancreatic endocrine tumors (1 paper, 2020). "While expression profile analysis of pancreatic endocrine tumors revealed an overexpression of Bin1 gene, expression of Bin1 in PADC cells has not been analyzed so far." (PMID 32384638, 2020).
prostate adenocarcinoma (1 paper, 2017). "The bridging integrator 1 (BIN1) protein, originally identified as a MYC-interacting tumor suppressor, is frequently missing in primary prostate adenocarcinoma, where MYC is deregulated." (PMID 28212321, 2017).
ptosis (1 paper, 2013). The drooping of the upper eyelid. "Classical BIN1-related ARCNM has been described with neonatal or childhood onset, hypotonia and ptosis and all mutations were found in ubiquitously expressed exons." (PMID 23754947, 2013).
Respiratory insufficiency (1 paper, 2021). "Respiratory insufficiency was most frequently observed in male MTM1 patients, but occurred also in the other subgroups of CNM except for BIN1 patients." (PMID 34463354, 2021).
Senile plaques (1 paper, 2022). Senile plaques are extracellular deposits of amyloid in the gray matter of the brain. "BIN1 directly interacts with RIN3 to initiate RAB5-mediated endocytosis, which is essential for β-secretase (BACE1)-mediated β-secretase cleavage of β-amyloid precursor protein (APP) to generate Amyloid-β (Aβ), the key component of senile plaques in AD." (PMID 35241726, 2022).